RIPK1 (receptor interacting serine/threonine kinase 1)
Diseases named in the same sentence as RIPK1 in open-access papers (continued):
Sharing a sentence is not in itself a finding about the gene and the disease.
ischemic stroke (continued). "Therefore, the CasRx-mediated knockdown of Ripk1 and Nsf holds promise for future therapeutic applications aimed at ameliorating cerebral lesions and neurological deficits following ischemic stroke." (PMID 38919602, 2024). "In the middle cerebral artery occlusion (MCAO) model in vivo and the oxygen–glucose deprivation/re-oxygenation (OGD/R) cellular model in vitro, blocking the RIPK1/RIPK3/MLKL pathway could effectively alleviate ischemic stroke injuries." (PMID 38026442, 2023). "Necroptosis revealed that the programmed cell death necrosis mechanism is induced in ischemic stroke, triggered by the phosphorylation of receptor-interacting protein kinase-1 (RIPK1), receptor-interacting protein kinase 3 (RIPK3), and mixed lineage kinase domain-like (MLKL)." (PMID 37681864, 2023). "However, how RIPK1 regulates lysosomal membrane instability in nerve cells under ischemic stroke and other disease conditions is still unknown." (PMID 37055533, 2023). "By intervening in the RIPK1/RIPK3/MLKL pathway, previous studies have demonstrated that necroptosis contributes to ischemic stroke." (PMID 38026442, 2023). "Several studies have indicated that ROS generation leads to PARP activation, AIF release, RIPK1 autophosphorylation, RIPK3 recruitment and NLRP3 inflammasome activation in response to ischemic stroke." (PMID 38026442, 2023). "Several studies have demonstrated that RIPK1, RIPK3 and MLKL participate in the pathogenesis of ischemic stroke after the activation of DRs." (PMID 38026442, 2023). "Recently, it was shown for the first time that p-RIPK1- (Ser166) and RIPK3/MLKL-dependent necroptosis pathways are activated in the modeling of ischemic stroke." (PMID 35054920, 2022). "In conclusion, the downregulation of Ripk1 mRNA and Nsf mRNA mediated by CRISPR-CasRx holds promise for future therapeutic applications aimed at ameliorating cerebral lesions and neurological deficits following the ischemic stroke." (PMID 38919602, 2024). "In ischemia–reperfusion injury, the upregulation of RIPK1 and RIPK3 results in CypD-mediated mPTP opening, Ca2+ influx and ROS generation, and the inhibition of CypD-mediated mPTP opening could alleviate ischemic stroke-induced necroptosis." (PMID 38026442, 2023). "We found that Nec-1, but not iNec, inhibited activation of RIPK1 and its downstream targets after ischemic stroke." (PMID 31440386, 2019). "However, the precise mechanism by which NSF and RIPK1 cooperate to initiate necroptosis remains unclear, and the role of NSF in ischemic stroke is a subject of controversy." (PMID 38919602, 2024). "However, the mechanism underlying the sequential recruitment of receptor-interacting protein kinase 1 (RIPK1) and N-ethylmaleimide-sensitive fusion ATPase (NSF) in initiating necroptosis remains poorly understood, and the role of NSF in ischemic stroke is a subject of controversy." (PMID 38919602, 2024). "Finally, in accordance with other papers demonstrating that COVID‐19 patients had more severe ischemic strokes with worse outcomes, we found that S1rp increased oxygen glucose deprivation/reoxygenation‐induced toxicity in an additive manner, via the NRP1/HDAC4/CREB/RIPK1 pathway." (PMID 40746867, 2025).
ischemia (13 papers, 2017 to 2024). A hypoperfusion of the BLOOD through an organ or tissue caused by a PATHOLOGIC CONSTRICTION or obstruction of its BLOOD VESSELS, or an absence of BLOOD CIRCULATION. "The reduction in infarct and edema volume in the CasRx-Ripk1-Nsf group following tMCAO suggests that the knockdown of Ripk1 and Nsf provides a certain level of protection against ischemia brain injury." (PMID 38919602, 2024). "The process involves ischemia and oxidative stress-induced cardiac injury, as follows: the classical necroptotic pathway is usually initiated by the phosphorylation of RIPK1, which further phosphorylates RIPK3." (PMID 37383699, 2023). "In the “Ischemia+ RIPK1 inhibitor” group, one animal failed one attempt to find the hidden platform on the third learning session." (PMID 35054920, 2022). "Our work aimed at studying the effects of receptor-interacting protein kinase 1 (RIPK1) inhibition on the functional activity of neural networks in primary hippocampal cultures in modeling key factors of ischemia in vitro." (PMID 35054920, 2022). "In this study, we showed that p-RIPK1 (Ser166) induced by ischemia triggered the RIPK3/MLKL-dependent necroptotic pathway." (PMID 31440386, 2019). "In conclusion, our study was the first to demonstrate that p-RIPK1 (Ser166) increases in the brain after ischemia, which then activated the RIPK3/MLKL-dependent necroptotic signaling pathway to cause neuronal death." (PMID 31440386, 2019). "Therefore, we assessed the neuroprotective potential of the Nec-1, RIPK1 inhibitor, using two models: modeling glucose deprivation and acute normobaric hypoxia in vitro as key damaging factors of ischemia." (PMID 35054920, 2022). "We also demonstrated that ischemia-induced RIPK1-mediated RIPK3/MLKL necroptosis was specific because Nec-1 treatment could significantly inhibit ischemia-induced increase of RIPK3, MLKL and p-MLKL expressions as well as attenuate ischemic brain injury via inhibition of RIPK1 kinase activity." (PMID 31440386, 2019). "The levels of three core components of necrotic pathways, RIPK1, RIPK3 and MLKL significantly increased during 6–24 h of ischemia developed after the beginning of reperfusion, while cleaved caspase-8 was reduced." (PMID 30158627, 2018).
ovarian carcinoma (13 papers, 2014 to 2025). A malignant neoplasm originating from the surface ovarian epithelium. "The aim of this study was to explore the associations of RIPK1 polymorphisms, plasma levels and mRNA expression with susceptibility to epithelial ovarian cancer (EOC) and clinical outcome." (PMID 37996860, 2023). "In pancreatic and ovarian cancer cells, 6-methoxydihydroavicine activates the RIPK1/caspase axis leading to disruption of oxaloacetic acid metabolism and alters mitochondrial respiration to induce MAPK-mediated apoptosis." (PMID 40630130, 2025). "The RIPK1/PARP pathway plays a critical role in mediating CS-piscidin-induced ovarian cancer cell death." (PMID 37000327, 2023). "We observed colocalization of both SOX9 and RIPK1 proteins in the cytoplasm, supporting their interaction in human ovarian cancer cells." (PMID 35159173, 2022). "Next, to confirm SOX9-RIPK1 interaction in human ovarian cancer cells, MDAH 2774 cells with high SOX9 and RIPK1 protein levels were subjected to immunoprecipitation followed by immunoblotting." (PMID 35159173, 2022). "In order to investigate the functional significance of SOX9-RIPK1 interaction in ovarian cancer cells, 2774 cells were transfected with RIPK1-specific siRNA or control siRNA, and CDDP sensitivity and cell invasion ability were determined." (PMID 35159173, 2022). "Consistent with the interaction results in a yeast system, a co-immunoprecipitation assay with anti-SOX9 and anti-RIPK1 showed an interaction between them in ovarian cancer cells." (PMID 35159173, 2022). "Prevention of cancer cell death by protein interaction between stemness-regulating SOX9 and RIPK1 contributes an evasion of an apoptotic cell death in devastating ovarian cancers." (PMID 35159173, 2022). "In these cells, death was dependent on RIPK1,pointing to necroptosis as a potential avenue to overcome resistance to apoptosis incancer cells, and improve outcome in women whose ovarian cancers express endogenously lowCaspase8." (PMID 28179987, 2015). "Moreover, in ovarian cancer, it was reported that the knockout (KO) of RIPK1 reduced cell proliferation and tumor growth in a mouse xenograft tumor model." (PMID 40565018, 2025). "It does so by regulating RIPK1 expression, thereby inhibiting the progression of ovarian cancer." (PMID 40305291, 2025). "This is supported by the observations that the inhibition of RIPK1 and MLKL protect from vaccinia-mediated necroptosis in ovarian cancer cell." (PMID 30665407, 2019). "We first investigated the expression of RIPK1, RIPK3, caspase-8 and MLKL in a panel of ovarian cancer cell lines as well as HeLa cells." (PMID 29238045, 2017). "The inhibition of RIPK1 and its substrate MLKL attenuate ovarian cancer cell death." (PMID 30665407, 2019). "Stabilization of RIPK1 and rise inMLKL, in the setting of decreased caspase activation and decreased PARP cleavage,suggest that IKKβ-inhibited, Caspase8-depleted ovarian cancer cells dieby necroptosis, a RIPK1-dependent, Caspase8-independent form of programmed celldeath." (PMID 28179987, 2015). "By contrast, the knockdown of the adaptor protein FADD had a more modest effect, suggesting that FADD may provide some facilitating role in necroptosis in the ovarian cancer cells, yet was not critical in facilitating RIPK1 to RIPK3 signaling." (PMID 25356865, 2014).
autoimmune disease (11 papers, 2016 to 2025). A disorder resulting from loss of function or tissue destruction of an organ or multiple organs, arising from humoral or cellular immune responses of the individual to their own tissue constituents. "Mutations in the RIPK1 gene have been linked to various diseases, including autoimmune disorders with established human causality." (PMID 41019071, 2025). "It has been reported that RIPK1-mediated necroptosis is associated with autoimmune diseases." (PMID 36993980, 2023). "Furthermore, our data pointed out the importance of studying the potential relationship between the genetic polymorphism of Ripk1 gene and the predisposition to more severe liver damage in hepatic infectious or autoimmune diseases." (PMID 27831558, 2016). "Accumulating evidence highlights RIPK1 as a promising therapeutic target for various human diseases, including neurodegenerative disorders, autoimmune diseases, and cancer." (PMID 41334873, 2025). "Recent studies have shown that RIPK1-dependent necroptosis plays an important role in autoimmune diseases, including RA." (PMID 36993980, 2023). "In fact, small molecular inhibitors of TAK1 or IKKβ are capable of inducing RDA in a TNF-dependent manner in some cancer and autoimmune disease models by dysregulating RIPK1 phosphorylation." (PMID 36171264, 2022). "Pathogenic mutations in genes encoding multiple regulators of the NF-κB pathway and the RIPK1 activation, including TNFR1, NEMO, A20, LUBAC and OTULIN, have been found in patients with autoinflammatory and autoimmune diseases." (PMID 34163478, 2021). "In addition to these autoimmune diseases, for the first time, we demonstrate the involvement of RIPK1 in AA progression and the possibility of applying RIPK1 inhibitors for AA prevention." (PMID 40004031, 2025). "The development of RIPK1 inhibitors, such as GSK′772 for peripheral autoimmune diseases and DNL747 for central nervous system disorders, highlights their potential therapeutic application in mitigating the detrimental effects of RIPK1 activation." (PMID 38672167, 2024).
Cognitive impairment (11 papers, 2018 to 2025). Abnormal cognition is characterized by deficits in thinking, reasoning, or remembering. "Inhibiting RIPK1 by Nec-1 strikingly alleviated postoperative cognitive impairment and amplified neuroinflammation, necroptosis and GluA1 loss in hippocampus." (PMID 30042663, 2018). "Therefore, activated RIPK1 appears to be an essential mediator of neuroinflammation in a high‐glucose environment and is a potential therapeutic target for cognitive disorders linked to T2DM." (PMID 37665158, 2024). "We propose that increased neuroinflammation in chronic hyperglycemia may be due to overexpression of RAGE, subsequent RIPK1 phosphorylation in microglia, and activation of the associated signal transduction pathway and that these changes ultimately lead to cognitive deficits." (PMID 37665158, 2024). "Another study showed that neuron-specific deficiency of RIPK1 or RIPK3 significantly enhances cognitive performance of TBI mice, indicating that RIPK1 or RIPK3 serve as viable therapeutic targets for post-TBI cognitive impairment." (PMID 41369366, 2025). "Necroptosis, a form of programmed cell death mediated by receptor-interacting protein kinases 1 and 3 (RIPK1/3) and mixed lineage kinase domain-like protein, has been implicated in PTX-induced cognitive impairment." (PMID 40322465, 2025). "Our results suggest that the binding of RAGE to RIPK1 via the AAs 362–367 motif is a key molecular mechanism that enhances neuroinflammation and cognitive deficits in high‐glucose conditions." (PMID 37665158, 2024). "Our study suggests that blocking the interaction between RAGE and RIPK1 significantly downregulates the intracellular inflammatory signaling pathway, ultimately alleviating cognitive deficits in db/db mice." (PMID 37665158, 2024). "Morin, a plan-derived flavonol, was able to prevent cognitive deficits, necroptosis, and mitochondrial damage in a rat model of neurodegeneration, apparently through Ripk1 inhibition (Abd El-Aal, El-Abhar & Abulfadl, 2022)." (PMID 38274328, 2024). "Direct interaction of RAGE and RIPK1 via AAs 362–367 is an important mechanism for enhanced neuroinflammation in the hyperglycemic environment and is a key node in the development of cognitive deficits in diabetes." (PMID 37665158, 2024). "Our findings indicate that RAGE promotes diabetes‐induced neuroinflammation and cognitive impairment via direct binding of AAs 362–367 to RIPK1 in microglia and subsequent activation of a microglial inflammation‐related signaling pathway." (PMID 37665158, 2024). "Receptor-interacting protein kinase 1 (RIPK1), a key molecule mediating necroptosis and regulated by transforming growth factor β-activated kinase 1 (TAK1), was reported to be associated with cognitive impairment in several neurodegenerative diseases." (PMID 37329446, 2023). "A recent study showed that inhibiting RIPK1 activation suppressed neuroinflammation and attenuated cognitive impairment following surgery." (PMID 37329446, 2023). "Inhibiting RIPK1 by Nec-1 strikingly alleviated postoperative cognitive deficits and neuroinflammation." (PMID 30042663, 2018). "We found that inhibiting RIPK1 by Nec-1 significantly mitigated postoperative cognitive deficits and alleviated perioperative neuroinflammation in aged mice." (PMID 30042663, 2018). "Inhibiting RIPK1 by necrostatin-1 strikingly mitigated cognitive impairment and alleviated postoperative amplified neuroinflammation, necroptosis and GluA1 loss in hippocampus." (PMID 30042663, 2018). "We found that, TAK1 knockdown in RHRSP markedly increased neuronal apoptosis and necroptosis and induced cognitive impairment, which could be reversed by Nec-1s, an inhibitor of receptor interacting protein kinase 1 (RIPK1)." (PMID 37196118, 2023).
Cognitive impairment (continued). "We further found that the TAK1 inhibitor takinib triggered RIPK1 upregulation, astrocyte and microglial activation, hippocampal neuroinflammation and cognitive impairment after surgery, but these changes were reversed by the RIPK1 inhibitor Nec-1 in young rats." (PMID 37329446, 2023). "So we tried to detect whether inhibiting RIPK1 by Nec-1 could limit neuroinflammation and alleviate postoperative cognitive deficits." (PMID 30042663, 2018). "Our aim was to investigate whether inhibiting RIPK1 by Nec-1 could limit neuroinflammation and attenuate postoperative cognitive deficits in D-Gal-induced aged mice." (PMID 30042663, 2018). "Pharmacological and genetic inhibition of RIPK1/3 and MLKL have effectively ameliorated pathological changes and cognitive deficits in AD animal models." (PMID 40787447, 2025). "Using Necrostatin-1 (Nec-1), a specific RIPK1 inhibitor, we successfully inhibited necroptosis and improved cognitive function in a mouse model of PTX-induced cognitive impairment." (PMID 40322465, 2025). "Direct binding of RAGE AAs 362–367 to RIPK1 is responsible for activation of RIPK1 and the NLRP3 inflammasome, leading to subsequent cognitive deficits." (PMID 37665158, 2024). "RAGE binds directly to RIPK1 via the amino acid sequence (AAs) 362–367, thereby upregulating phosphorylation of RIPK1, which results in activation of the NLRP3 inflammasome in microglia and ultimately leads to cognitive impairments in db/db mice." (PMID 37665158, 2024). "Notably, knockdown of TAK1, mediated by AAV-siTAK1, significantly increased RIPK1-caspase 8-mediated apoptosis and RIPK1-RIPK3-MLKL dependent necroptosis of neurons in the cerebral cortex and hippocampus, which was accompanied by the decrease of neurons and cognitive impairment." (PMID 37196118, 2023).
liver disease (11 papers, 2016 to 2025). "Although we did not observe any protective effects of RIPK3 deficiency in these ALF models, RIPK1-MLKL-mediated necroptosis independently of RIPK3 had been implicated in other liver diseases." (PMID 35853848, 2022). "Attention was drawn to RIPK1 in the context of liver disease due to the discovery of Nec-1, an inhibitor of RIPK1 kinase." (PMID 40007541, 2025). "Several previous studies have shown that inhibition of RIPK1 or MLKL can retard the progression of liver disease." (PMID 37828052, 2023). "A previous genetic study suggested that RIPKs were implicated in the pathogenesis of liver disease by regulating caspase-dependent hepatocyte apoptosis, and RIPK1/3 participated in many experimental liver disease models." (PMID 33329521, 2020). "In conclusion, our results suggest that RIPK1 kinase activity is a pertinent therapeutic target to protect liver against excessive cell death in liver diseases." (PMID 27831558, 2016). "Finally, our results support also that RIPK1 kinase activity is a pertinent therapeutic target to protect liver against excessive cell death in liver diseases." (PMID 27831558, 2016). "Previous studies reported that short-term HFD feeding was not enough to induce hepatic disorder, without obvious effects on the serum ALT/AST, liver histology, and our results with Ripk1-Con mice were in agreement with these findings." (PMID 39886919, 2025).